IGFBP3 (insulin like growth factor binding protein 3)
Diseases named in the same sentence as IGFBP3 in open-access papers (continued):
Sharing a sentence is not in itself a finding about the gene and the disease.
prostate carcinoma (continued). "The A allele of functional SNP rs2854744 in the promoter region of IGFBP3 has been associated with higher levels of IGFBP-3 and may be associated with reduced breast and prostate cancer risk." (PMID 22253814, 2012). "Also with regard to prostate cancer, decreased expression of IGFBP-3 is correlated with increased risk of developing prostate cancer." (PMID 19094237, 2008). "Fifteen studies investigated whether genetic or epigenetic variations in the IGF-I (n = 5), IGF-II (n = 7), IGFBP-2 (n = 2) or IGFBP-3 (n = 3) gene were associated with prostate cancer risk or outcomes such as Gleason score, TNM stage, PSA recurrence or survival." (PMID 28361446, 2017). "Finally, if rs700752 is employed as an IV for serum IGF‐I and IGFBP‐3, based on ProtecT findings, the causal estimates regarding prostate cancer‐specific mortality were HR 0.72 (95% CI: 0.53, 0.98) per SD increase in IGF‐I, and HR 0.76 (95% CI: 0.60, 0.95) per SD increase in IGFBP‐3." (PMID 27225428, 2016). "Interestingly, inhibition of IGFBP-4 expression in prostate cancer cells also lead to the suppression of cancer cell growth which may be caused by greatly increased levels of IGFBP-3 and -6 in these cells." (PMID 24175938, 2013). "Furthermore, quercetin also deserves study in the context of prostate cancer preventions, because others have recently shown in populations studies that higher circulating IGFs level and/or lowers IGFBP-3 levels are associated with increased risk of prostate cancer." (PMID 16600019, 2006). "This protein has previously been reported as a regulator of beta cells and as a cell death receptor in breast and prostate cancers and is activated by its ligand, insulin-like growth factor binding protein 3 (IGFBP3)." (PMID 40371644, 2025). "CDK12 inhibits insulin-like growth factor binding protein 3 (IGFBP 3) in regulating angiogenesis in advanced prostate cancer." (PMID 39790460, 2025). "Early studies have indicated that IGFBP3 suppresses the growth of lung cancer, liver cancer, and prostate cancer cells." (PMID 38326861, 2024). "Studies have uncovered that when Tf binds to insulin-like growth factor binding protein 3 (IGFBP-3), it loses its capacity to stimulate bladder smooth muscle proliferation and induce apoptosis in prostate cancer cells." (PMID 38500764, 2024). "Other examples include the P-score, which consists of the expression of three genes, among which is IGFBP3, and adds to the prognosis for prostate cancer patients." (PMID 38255186, 2023). "Excessive expression of IGFBP3 dominantly repressed cell growth in prostate cancer, and the enhancement of docetaxel cytotoxicity in prostate cancer cells by low-dose dihydrotestosterone/calcitriol depended on IGFBP3 expression." (PMID 36660244, 2023). "The tumor suppressor features of miRNA-642 was also confirmed by an alteration of expression of potential target genes, such as WT1, NUAK1, RASSF3, SKP2, GPS2 and IGFBP3, in prostate cancer." (PMID 37108073, 2023). "The lower the level of IGFBP3 in the plasma of prostate cancer patients is, the more likely they are to develop bone metastasis." (PMID 38062230, 2023). "Our study discovered the phenome-wide exposed-omics risk factors profile of prostate cancer, and verified that the IGFBP-3, DHA, BMI, and SLE were causally related to prostate cancer risk." (PMID 35237523, 2022). "To further explore the correlation of IGFBP3 status to IGF1 activation in human prostate cancer samples, we employed HiSeq RNA sequencing data from TCGA (The Cancer Genome Atlas) and GEO (GSE197780) datasets." (PMID 36323713, 2022). "Apigenin treatment successfully slowed the progression of prostate cancer in mouse models by lowering IGF/IGFBP-3 and reducing p-AKT and p-ERK1/2 expression." (PMID 35807549, 2022).
prostate carcinoma (continued). "The Mendelian randomization analysis verified the IGFBP-3, DHA, BMI, and SLE were causally related to prostate cancer risk." (PMID 35237523, 2022). "IGFBP‐3 is a strong anti‐proliferative protein that provokes apoptosis and inhibits cell proliferation in human prostate cancer." (PMID 34015193, 2021). "1,25(OH)2D3–mediated increased mRNA expression of IGFBP3 was observed in LNCaP prostate cancer cells and RWPE1 cells (immortalized prostate epithelial cell line)." (PMID 34208589, 2021). "Nuclear IGFBP-3 has been identified in human keratinocyte cell line and human prostate cancer tissues; indeed, this protein is known to have a functional nuclear localisation signal." (PMID 32093285, 2020). "IGFBP-3 protein level decreased in the process of prostate cancer metastasis from benign to malignant." (PMID 33414813, 2020). "IGFBP3 exhibits antitumor effect in prostate carcinoma through crosstalk with the NF-κB pathway and activation of caspase-dependent apoptosis." (PMID 33282953, 2020). "IGFBP-3 was also found to be a mediator of the enhanced cytotoxicity of prostate cancer cells to VD3 in combination with the anti-cancer drug." (PMID 32831047, 2020). "IGFBP-3 is also a potent inhibitor of MAPK signalling, which is implicated in the development of castrate-resistant prostate cancer." (PMID 32056047, 2020). "The transfection of prostate cancer, PC-3 cells with IGFBP-3 resulted in apoptosis, however, PC-3 cells co-transfected with E7 and IGFBP-3 displayed reduced apoptotic cell death." (PMID 32478064, 2020). "Previously, it has been reported that higher concentration of synthetic androgen analogue (R1881) or DHT treatment also induced IGFBP-3 expression in prostate cancer cells." (PMID 32831047, 2020). "The repressed gene set included mainly genes involved in signaling and tumor progression, such as IGFBP3, a metastasis/angiogenesis suppressor in prostate cancer." (PMID 32155117, 2020). "Yet another study has demonstrated that a novel agent DZ-50 inhibits invasive properties of prostate cancer cells by specifically targeting IGFBP3 and mediating mesenchymal-to-epithelial transition (MET)." (PMID 32414222, 2020). "Molecular dissect of IGFBP-3 function on cell growth in prostate cancer cells in vitro and monitoring of IGFBP-3 in response to VD3 treatment, castration or androgen-deprivation therapy in patient’s prostate tumor would be future challenge." (PMID 32831047, 2020). "In prostate cancer cells exogenous supplementation of IGFBP-3 resulted in induction of apoptosis through the export of orphan nuclear receptors, Nur77 and its binding partner, RXR-α." (PMID 32478064, 2020). "Here, we wondered if continual VD3 treatment would be required for maintaining IGFBP-3 induction in prostate cancer cells." (PMID 32831047, 2020). "Several opponent studies regarding IGFBP-3 on growth inhibition in prostate cancer cells have been reported." (PMID 32831047, 2020). "In lung cancer, however, circulating IGFBP-3 has an inverse correlation with cancer risk, while IGFBP-3 plasma levels in prostate cancer are associated with cancer incidence and survival." (PMID 32093285, 2020). "IGFBP3 upregulation in the tumor stroma of prostate cancers has been demonstrated by gene expression profiling following laser‐capture microdissection and it has been suggested its role as mediator for tumor–stroma interactions." (PMID 32767843, 2020). "Considering these findings, we believe that IGFBP-3 can be a key molecule for VD3 treatment in prostate cancer cells." (PMID 32831047, 2020).
prostate carcinoma (continued). "Vitamin D has been reported to increase IGFBP-3 expression in prostate cancer LNCaP cells, an androgen dependent cell line resulting in decreased cell proliferation, in part." (PMID 32478064, 2020). "IGFBP3 levels are significantly elevated in prostate cancer patients urine and is consistent with our data." (PMID 31303963, 2019). "The potential roles of IGFs and IGFBPs in mediating cell movement and migration have been studied more so in cancer cells than in stromal stem cells, for, for example, degradation of IGF‐1/IGFBP3 complex by MMP‐9‐triggered prostate cancer cell migration." (PMID 29321953, 2018). "Decreased protein intake and body mass index, and increased physical activity and fruit and vegetable intake, following a prostate cancer diagnosis were associated with reduced post-diagnosis serum IGF-I and IGFBP-3." (PMID 28646365, 2017). "Clinical evidence has established a positive correlation between elevated IGF-1Rs in prostate stroma tissue and Gleason grade, and down-regulation of epithelial IGFBP3 in prostate cancer patients." (PMID 29108245, 2017). "We found that DZ-50 antagonized TGF-β1-promoted cell invasion by targeting IGFBP3 in both prostate cancer epithelial cells and CAFs, supporting its therapeutic value." (PMID 29108245, 2017). "The intrinsically active TGF-β signaling in the LNCaPTβRII prostate cancer cells antagonized the inhibitory effect of DZ-50 on IGFBP3 expression." (PMID 29108245, 2017). "Our findings demonstrate that the lead compound, DZ-50, inhibited the invasive properties of prostate cancer epithelial cells by targeting IGFBP3 and mediating EMT conversion to MET." (PMID 29108245, 2017). "Here we propose a new effect of DZ-50 on nuclear IGFBP3 mediating the pharmacologic reversion of EMT to MET in prostate cancer cells." (PMID 29108245, 2017). "Positioning a role for IGFBP3 in the tumor microenvironment, elevated IGFBP3 in stroma tissue was found in pre-clinical models of prostate cancer resonating with the evidence in human prostate cancer specimens." (PMID 29108245, 2017). "A better understanding of functional interactions between fibroblasts and tumor epithelial cells, as mediated by IGFBP3, will define the role of stroma to therapeutic resistance in advanced prostate cancer." (PMID 29108245, 2017). "This study provides the first evidence on the impact of our lead quinazoline agent, DZ-50, on EMT reversion to the MET phenotype in different human prostate cancer cell lines and in co-culture cell models (with CAFs), via targeting IGFBP3." (PMID 29108245, 2017). "In conclusion, decreased protein intake and BMI, and increased fruits and vegetables intake and physical activity, following a prostate cancer diagnosis were associated with reduced post-diagnosis serum IGF-I and IGFBP-3." (PMID 28646365, 2017). "It regulates multiple downstream genes including IGFBP3 (also present in our network) which is a pro-apoptotic and anti-angiogenic protein in prostate cancer and activates caspase 3 and caspase 8, and subsequently induces cell apoptosis." (PMID 28005952, 2016). "A deeper look into the IGFBP1/IGFBP3 region revealed at least two independent signals of association with prostate cancer following the regional LD structure (excluding rs700752): one toward the IGFBP1 gene, and one encompassing the IGFBP3 gene." (PMID 27225428, 2016). "Rs700752 was associated with prostate cancer‐specific mortality, with the allele that increases IGF‐I and IGFBP‐3 levels (major) being associated with a lower risk of death." (PMID 27225428, 2016). "We have also detected associations of SNPs in IGFBP‐1/IGBP‐3 with prostate cancer aggressiveness which suggest a positive relationship with higher circulating IGF‐II and possibly IGFBP‐3 (this varies depending on the instrument used)." (PMID 27225428, 2016).
prostate carcinoma (continued). "This indicates Gleason score and two genes (IGFBP3 and F3) would provide the largest two weights for predicting overall survival in prostate cancer patients using a combined model including genes and clinical parameters together." (PMID 26731648, 2016). "In prostate cancer cell line vitamin D led to upregulation of insulin-like growth factor binding protein-3 (IGFBP3), which can inhibit cell cycle through upregulation of p21 expression." (PMID 27058533, 2016). "In order to obtain a more complete picture of the IGFBP1/IGFBP3 genetic region and its relationship to prostate cancer, we carried out an analysis of all additional SNPs within these genes that were available in PRACTICAL (n = 39)." (PMID 27225428, 2016). "Being a suppressor, several studies have confirmed that IGFBP3 suppresses cell adhesion, invasiveness of endometrial cancer, metastasis in prostate cancer, and angiogenesis in head and neck squamous cell carcinoma." (PMID 26540630, 2015). "Reduced IGFBP3 expression has been reported in several cancers such as lung cancer, hepatocellular carcinoma, ovarian cancer and prostate cancer." (PMID 26540630, 2015). "The gene expression levels of IGFBP3 and F3 in prostate cancer epithelial cell-containing tissue representing the primary and secondary Gleason patterns were high and consistent, while the low expressed VGLL3 showed more variation in its expression levels." (PMID 25296164, 2014). "Fat intake is also negatively correlated with insulin-like growth factor binding protein-3 (IGFBP-3), the major binding protein of IGF-1 in plasma, which is also independently associated with the risk of prostate cancer." (PMID 25533015, 2014). "In prostate cancer, for example, IGFBP3 protein levels decrease when cells progress from benign to malignant metastasis." (PMID 24084056, 2013). "Recent evidence indicates increased risk of prostate cancer in individuals with high serum IGF1 levels, whereas risk was decreased in those with high levels of IGFBP-3." (PMID 22792137, 2012). "The SNPs in LEPR Gln223Arg, SPP1-66 T>G, IGF1R+3174 G>A, IGFBP3-202 A>C, FGF2+223 C>T and IL6-597 G>A, plus age and PSA remained independently associated with risk for overall, and for high-grade prostate cancer." (PMID 22792137, 2012). "Other genes act as tumor suppressors, such as IGFBP3, which inhibits prostate cancer growth through suppression of angiogenesis, and LCN2, which increases the expression of E-cadherin and suppresses cell invasiveness." (PMID 22328933, 2012). "GH and IGF1 levels decline with aging, concordant with loss of muscle and bone mass and an increase in fat deposition and BMI, and selected studies have reported an association between prostate cancer and blood IGF1 or genetic variants in IGF1 or IGFBP3." (PMID 22257467, 2012). "IGFBP3 methylation was detected in 49/79 (62.03%) of the prostate cancer samples at sequence A, 15/79 (19.23%) at sequence B and 0/79 (0%) at sequence C." (PMID 17453001, 2007). "Using three QMSP assays, we found tumour-related differential methylation of the IGFBP3 promoter CpG island in prostate cancer." (PMID 17453001, 2007). "In the prostate cancer cell line PC-3, the addition of exogenous IGFBP-3 resulted in a dose-dependent increase in the apoptotic index, which was only partly attenuated by the addition of IGF-I." (PMID 17210081, 2007). "Recent evidences suggest that silibinin, a commonly occurring flavonoid can inhibit the IGF-I secretions, and increase the level of IGFBP-3 and induce of apoptosis in both in vivo and in vitro model of prostate cancer." (PMID 16600019, 2006). "This study was designed to investigate its effects on insulin-like growth factors (IGFs) and their binding protein-3 (IGFBP-3) proteins secretion and also apoptosis induction in the human prostate cancer cell line, PC-3." (PMID 16600019, 2006).
prostate carcinoma (continued). "Our previous study showed that quercetin reduce, IGF-I protein secretion in conditioned media, while IGFBP-3 was induced in prostate cancer cells." (PMID 16600019, 2006). "IGFBP-3 is expressed in many tissues including prostate and others have demonstrated its growth inhibitory effects in human prostate cancer cells as well as in IGFRI-null fibroblasts." (PMID 16600019, 2006). "Decreased levels of IGFBP3 was noted in prostatic cancers when compared to normal prostate epithelium (p = 0.0044)." (PMID 15318950, 2004). "Circulating levels of IGF-I and IGFBP-3 are likely to be higher in prostate cancer patients than in the controls." (PMID 11592771, 2001). "This study and related literature have confirmed that serum IGF-I and its related molecules (such as IGFBP-3 and pregnancy-associated plasma protein-A [PAPP-A]) are closely associated with the risk of prostate cancer, especially playing an important role in risk stratification and early warning." (PMID 41584612, 2025). "Similarly, IGFBP-3 was significantly increased in the early stages of prostate cancer, providing important evidence about the role of IGF signaling." (PMID 37510722, 2023). "Notably, 1,25(OH)2D3 and vitamin D analogs were found to activate the accumulation of IGFBP3 in primary prostate epithelial cell and prostate cancer cells." (PMID 34208589, 2021). "In addition, in metastatic prostate cancer cells, the pharmacological inhibition of IGFBP3 enhanced response to enzalutamide, an antiandrogen therapy, through EMT reversion." (PMID 34944855, 2021). "Here, we supposed that IGFBP-3 might be a mediator of VD3-induced sensitization to anticancer drugs in prostate cancer cells." (PMID 32831047, 2020). "However, while PRT has been shown to reduce plasma IGF-1 and increase IGFBP-3 levels in prostate cancer, current epidemiological studies in cancer populations show significant heterogeneity in the response of the systemic IGF axis to exercise." (PMID 32056047, 2020). "Further analysis if the amount of secreted IGFBP-3 was in parallel with that of intracellular IGFBP-3 to dissect the spatio-temporal function of IGFBP-3 would be important for in depth understanding how IGFBP-3 contributes in cell growth inhibition in patients with prostate cancer." (PMID 32831047, 2020). "In addition, the functional contribution of IGFBP3 to prostate cancer cell apoptosis, involves the IGFBP3-mediated translocation of Nur77 from the nucleus to mitochondria." (PMID 29108245, 2017). "IGF binding protein-3 (IGFBP3) induction is initiated by stroma remodeling and could represent a potential therapeutic target for prostate cancer." (PMID 29108245, 2017). "Here we investigate the association of changes in dietary intake or adherence to dietary and lifestyle recommendations with post-diagnosis circulating levels of IGF-I and IGFBP-3 in men diagnosed with prostate cancer in the Prostate testing for cancer and Treatment (ProtecT) randomized trial." (PMID 28646365, 2017). "Similarly, IGFBP-3 was found to mediate vitamin D-induced growth inhibition in LNCaP prostate cancer cells." (PMID 28417914, 2017). "Functional silencing of IGFBP3 in prostate cancer epithelial cells resulted in increased E-cadherin, while neither of the transcriptional repressors, Snail or ZEB1 mRNA expression was significantly affected (by IGFBP3 knockdown) begging the question as to its role in EMT-MET cycling." (PMID 29108245, 2017). "Seen together, gene expression of IGFBP3 and F3 in combination with clinical parameters such as Gleason score most probably has an important role to play in the stratification of newly diagnosed prostate cancer patients." (PMID 26731648, 2016). "IGFBP-3 is the most abundant IGFBP and serum level is positively associated with prostate cancer." (PMID 25502434, 2014).